IL6 (interleukin 6)
Diseases named in the same sentence as IL6 in open-access papers (continued):
Sharing a sentence is not in itself a finding about the gene and the disease.
psoriasis (continued). "We found that in the skin of psoriasis-like mice, Il1b and Il6 were mainly expressed in neutrophils, while Il17a was mainly expressed in T cells, Il18 was mainly expressed in macrophages and fibroblasts, and Tnfa was mainly expressed in macrophages and T cells." (PMID 39717896, 2024). "For example, studies have shown that IL-6 is significantly elevated in patients with psoriasis and may exacerbate skin inflammation by promoting T-cell activation." (PMID 39588112, 2024). "Similarly, we have demonstrated higher serum IL-6 levels in psoriasis patients than in control subjects." (PMID 39200092, 2024). "Elevated TNF-α, IL-1β, and IL-6 levels in psoriasis reduce triglyceride clearance." (PMID 38683749, 2024). "In the last 10–15 years, the introduction of biological therapies, such as TNF-α, IL-12/23, and IL-17 inhibitors in psoriasis and IL-6, CD20, TNF-α, and CD80/86 inhibitors in RA, is expected to influence the rate of atherothrombotic complications in patients with psoriasis and RA." (PMID 38927529, 2024). "Furthermore, we examined a set of inflammatory cytokines, including IL-17A, IL-23A, IL-1β, TNF-α, IL-6, and IL-22, at the mRNA level in LPS-induced psoriatic keratinocytes, which are closely related to psoriasis in vivo." (PMID 39109246, 2024). "Furthermore, TNF-α, interferon-γ (IFN-γ), IL-6, and IL-22 have also been reported to be increased in psoriasis." (PMID 39109246, 2024). "By measuring inflammatory markers (IL-6) and lipid profiles early in the disease process, we can employ preventive strategies to better manage and improve survival and quality of life in patients with psoriasis." (PMID 39429270, 2024). "In this study, we aimed to investigate whether patients with psoriasis have higher serum levels of miR-155 that lead to the downregulation of serum levels of IL-6." (PMID 39044928, 2024). "The longstanding psoriasis may be associated with the onset of UCD and the significantly down-regulated interleukin-6 level indicated a good therapeutic response." (PMID 38566262, 2024). "Interestingly, in line with the present findings, previous data that evaluated smaller populations reinforce the role of circulating IL-6 for the prediction of treatment response in psoriasis." (PMID 37634972, 2024). "In summary, C3bot inhibits the cytokine-induced expression of IL-6 and thus may have an impact on the pro-inflammatory immune response in the psoriasis-like phenotype." (PMID 37707681, 2024). "While the exact cause of psoriasis is not fully elucidated, it is believed that abnormal immune function, especially the excessive secretion of inflammatory factors such as IL-1β and IL-6, contributes substantially to its development." (PMID 37554338, 2023). "In addition to keratinocytes, macrophages, neutrophils, lymphocytes, and mast cells produce high levels of cytokines such as TNF-α, IL-1β, and IL-6 to maintain the positive feedback cycle in psoriasis." (PMID 37585684, 2023). "It has been reported that IL-6 expression could be reduced by thalidomide, leading to inhibition of the inflammatory response in psoriasis." (PMID 37298949, 2023). "Adoptive transfer with Tomato-expressing BMDMs restored Mincle-expressing macrophage infiltration and inflammatory responses as demonstrated by upregulation of pro-inflammatory cytokines (IL-1β and IL-6), Mincle and iNOS, resulting in the development of severe skin lesion in psoriasis mice." (PMID 37117184, 2023). "NLR and IL-6 may serve as predictive biomarkers of treatment response to TNF-α inhibitor therapy in patients with psoriasis." (PMID 37047086, 2023). "In patients with psoriasis, a high level of IL6 gene expression may be a marker for possible joint damage." (PMID 37246213, 2023). "In addition, some of these core NB-UVB-downregulated DEGs, such as IL36G and DEFB4A/B, were involved in IL-6 and IL-17 signaling, which are key cytokines in psoriasis pathogenesis." (PMID 36928592, 2023).
psoriasis (continued). "To further verify whether SFN could modulate the expression of inflammatory factors and chemokines during psoriasis development, we evaluated the mRNA levels of Il1b, Il6, and Ccl2 using qRT‒PCR." (PMID 38007430, 2023). "Interaction of S100A7 with RAGE activates p38 MAPK (mitogen-activated protein kinase) and ERK (extracellular signal-regulated kinase) signaling pathways, leading to production of multiple inflammatory mediators involved in psoriasis, including IL-1α, IL-1β, IL-6, IL-8, TNF-α." (PMID 37346040, 2023). "Ligilactobacillus and Anaeroplasma (inhibited in CUR mice) were positively correlated with multiple psoriasis‐related factors, such as IL‐6, IL‐17A, IL‐22, IL‐23, while Rikenella, Alistipes, and Mucispirillum (promoted in CUR mice) were negatively correlated with them." (PMID 37647442, 2023). "T regs in psoriasis patients have been reported to have reduced suppressive activity that normalizes with sodium butyrate administration and IL-10 levels and expression of Foxp3, IL-17, and IL-6 in psoriatic skin lesions." (PMID 37623895, 2023). "It has also been suggested that MAFLD could influence psoriasis severity by releasing inflammatory mediators from hepatocytes, including reactive oxygen species, C-reactive protein and interleukin-6." (PMID 37898739, 2023). "Importantly, these include IL‐6, IL‐21, and TGFb1 cytokines that have been shown to contribute to Th17 differentiation, a T cell subtype that marks psoriasis." (PMID 36855912, 2023). "Lastly, MAFLD could affect psoriasis severity through the release of inflammatory mediators from the hepatocyte, namely, reactive oxygen species, C-reactive protein and IL-6." (PMID 36836776, 2023). "Various cytokines and adhesion molecules, including interleukin (IL)-1, IL-2, IL-6, IL-8, IL-12, IL-18, TNF-α, and nerve growth factor, are abnormally expressed in the lesions of psoriasis patients, suggesting that psoriasis is associated with the release of NF-κB-regulated inflammatory cytokines." (PMID 36835162, 2023). "Moreover, IL-6 levels are positively correlated with clinical severity and effective treatment of psoriasis results in a reduction of IL-6 levels." (PMID 37373278, 2023). "Targeting cytokines such as TNFα, IL‐1 or IL‐6 might reduce mood and CI in systemic inflammation, as has been demonstrated in other conditions like psoriasis." (PMID 38146805, 2023). "Importantly, IL-6 suppresses Treg differentiation and IL-23 drives the polarization of Th17 cells, thus, both cytokines promote psoriasis progression." (PMID 36901755, 2023). "In addition, IMQ induces hyperproliferative keratinization in the epidermis and promotes the release of inflammatory factors such as IL-1 and IL-6, leading to psoriasis-like symptoms in the skin, which includes erythema, scaling, and epidermal thickening." (PMID 35566346, 2022). "The latest findings relating to IL-17F in psoriasis depict a quite ambiguous role, but show that it still may be the effector of IL-6 production, which is the pro-inflammatory cytokine entailing inflammation." (PMID 35203707, 2022). "Recently, the IP-mediated delivery of the TNF-α drug etanercept, the ultrasound-mediated delivery of miR-197, and the fractional laser-mediated delivery of small interfering RNA (siRNA) targeting interleukin-6 have all demonstrated promising results against the pathogenesis of psoriasis." (PMID 35335900, 2022). "Moreover, the horny cell of the patients with psoriasis can secrete IL-6, TNF alpha, IL-1 alpha, glucocorticoids, among others." (PMID 35948962, 2022). "Moreover, AEC-SC can also suppress the expression of other inflammatory factors IL-6 and TNFα, which are important for maintaining the inflammatory environment of psoriasis." (PMID 35922852, 2022).
psoriasis (continued). "Accumulative evidence indicates that regulatory T cells (Tregs) play a key role in psoriasis pathogenesis and that Treg dysfunction causes an aberrant release of proinflammatory cytokines, including tumor necrosis factor (TNF)-α, IL-6, IL-17, and IL-23, and activates NF-κB signaling." (PMID 35629363, 2022). "CAV-1 and the leptin receptor are co-localized in keratinocytes, and CAV-1 silenced human keratinocytes produce more IL-6 by co-stimulation with leptin and IL-17, suggesting that obesity deteriorates psoriasis by enhancing cytokine production in CAV-1 deficient psoriasis keratinocytes." (PMID 36532050, 2022). "IL-6 and IL-8 have been proven to play important roles in psoriasis." (PMID 35586566, 2022). "c-JUN activation could stimulate the production of inflammatory factor IL-6, thereby further aggravating the inflammatory response in psoriasis skin lesions." (PMID 35265149, 2022). "Moreover, IL-6-treated normal keratinocytes showed increased proliferation, suggesting the involvement of this proinflammatory cytokine in the hyperplasia of psoriasis." (PMID 35745702, 2022). "In psoriasis lesions, IL-6 and IL-1β are released from stimulated keratinocytes." (PMID 36620087, 2022). "In addition, etanercept reduced the levels of TNF‐α and IL‐6/12/23, and enhanced the levels of IL‐4/10, reduced Th17/Treg ratio and facilitated the polarization of macrophages to M2 in psoriasis model mice." (PMID 36444619, 2022). "Consequently, SHP2‐mediated TLR7/NF‐κB activation was augmented, leading to further increases in the expressions of psoriasis‐related inflammatory cytokines, including IL‐23A, TNF‐α, IL‐6, and IL‐1β, thus accelerating psoriasis‐like skin inflammation." (PMID 34936223, 2022). "IL-6 and/or IL-22 have pro-inflammatory activities toward lymphoid and myeloid lineage immune cells, and keratinocytes, which along with other cytokines drive their proliferation, differentiation and acute phase response observed in psoriasis." (PMID 36741386, 2022). "In the IMQ-induced psoriasis model, elevated expression levels of cytokines such as IL-17, IL-6, and IL-1 are attributed to the proliferation of macrophages, dendritic cells, mast cells, and neutrophils, and the increase in these factors suggests an inflammatory response." (PMID 35566346, 2022). "In addition, LL-37 has direct effects on keratinocytes and immune cells in psoriasis, thus supporting an active role for keratinocytes in the inflammatory cascade by releasing IL-1, IL-6, TNF-α cytokine, chemokines and type I interferons." (PMID 35883760, 2022). "TNF-α, a major mediator of psoriasis pathogenesis, has been shown to induce the expression of IL-6." (PMID 34158537, 2021). "Therefore, we examined the possible correlation of key cytokines (IL-1β, TNF-α, IL-4, and IL-6) known to drive crosstalk between KCs and immune sentinels, which results in psoriasis development, with the induction of miR-21-5p or miR-21-3p expression." (PMID 34685526, 2021). "IL-2R, IL-6, and IL-8 serum concentration in patients with psoriasis could be the predictor of disease severity and the marker of response to therapy." (PMID 33685393, 2021). "Cytokines or mediators that are upregulated in psoriasis, such as IL-23, IL-17A, IL-6, and IL-21, may induce the conversion of Tregs into Th17/Th1 cells." (PMID 34501328, 2021). "However, anti-IL6 therapy had side effects in smaller studies on psoriasis and UC and must be explored carefully." (PMID 34108969, 2021). "In addition, TNF-α, IL-6, and IL-1β are important proinflammatory cytokinesthat are related to the pathogenesis of psoriasis." (PMID 34202301, 2021). "In addition, betulinic acid attenuated psoriatic skin inflammation in a murine model of imiquimod-induced psoriasis via downregulation of pro-inflammatory mediators IL-6 and TNFα." (PMID 34314383, 2021).
psoriasis (continued). "IL-6 and IL-23 can stimulate IL-17F production in lesioned psoriatic skin compared with non-lesioned skin in humans, and it has been reported as one of the central cytokines in psoriasis development." (PMID 34884834, 2021). "In psoriasis mice induced by imiquimod, curcumin could improve the pathological injuries of the mouse skin, reduced the expressions of IL-6, p-STAT3, and its downstream proteins." (PMID 34337082, 2021). "Interestingly, adipose tissue also produces large amounts of proinflammatory cytokines, including TNF-α, IL-6 and IL-17, contributing to worsening of psoriasis." (PMID 34068473, 2021). "Anti-IL6 therapy (tocilizumab) showed a positive clinical response in a small group of patients in AS, CD, and RA, suggesting its application in other IMIDs like psoriasis and UC." (PMID 34108969, 2021). "Luteolin reduced IL-1β, IL-17A, IL-23, and IL-6 which could contribute to the anti-inflammatory effects of this flavonoid and the reduction of psoriasis damage in the mice model." (PMID 34943117, 2021). "However, the transcription of genes of key inflammatory mediators, such as S100 antimicrobial peptides, IL-6, and TNFα, which act synergistically to maintain an inflammatory response in psoriasis, can be activated by both sets of cytokines." (PMID 34877506, 2021). "Moreover, PPPs were observed to remarkably inhibit the levels of psoriasis-related pro-inflammatory mediators in the serum, namely, IL-17, IL-6, TNF-α, IL-8, and IL-23." (PMID 35153762, 2021). "Anti-TNF therapy has also been found to decrease IL-6 levels in patients with psoriasis." (PMID 34372872, 2021). "IL-17A is important in relieving psoriasis by upregulating cytokines IL-6, IL-1β, and TNF-α." (PMID 34054833, 2021). "At each step of the psoriasis molecular pathway, different inflammatory cytokines such as IL-6, IL-17, IL-22, and IL-23 are triggered, on the other side, growth factors such as EGF, VEGF, KGF, and IGF-1, which underscores the central role which predominantly drives epidermal hyperplasia." (PMID 33849555, 2021). "The Ki-67, as a cell proliferation marker in psoriasis skin, is regulated by the IL6/STAT3 pathway." (PMID 34445513, 2021). "In addition to the psychological stress caused by psoriasis, it has been reported that inflammatory cytokines are related to mood disorders, including elevated levels of cytokines, including TNF-a, IL-6 and IL-1." (PMID 34372872, 2021). "For this reason, IL-6 inhibitors could be a promising strategy for inhibiting the inflammatory response in psoriasis." (PMID 34948364, 2021). "In vivo studies showed that PSORI-CM02 markedly reduced angiogenesis in the skin of mice with IMQ-induced psoriasis, while significantly rebalancing antioxidant/oxidant levels; inhibiting the production of IL-6, TNF-α, IL-17A, and IL-17F; and repressing the synthesis of angiogenic mediators." (PMID 33995368, 2021). "Interestingly, pro-inflammatory cytokines associated with psoriasis such as TNF, IL-17 and IL-6 suppress melanin synthesis, but others can also activate the process." (PMID 34884858, 2021). "Blockade of IL-6 signaling decreases inflammation in PD-1 signal inhibition-provoked psoriasis-like dermatitis, and specifically, causes a reduction in the levels of Th17-related cytokines in a murine model of IMQ-induced psoriasis-like dermatitis." (PMID 33060784, 2020). "The cytokines of TNF-α and IL-6 play an important role in the development of psoriasis." (PMID 32448273, 2020). "Pro-inflammatory cytokines such as IL-1 and IL-6 are elevated both in psoriasis and depression." (PMID 32161545, 2020). "Collectively, these results suggest that the pathogenesis of anti-PD-1 antibody-induced psoriasis-like dermatitis may depend on IL-6." (PMID 33060784, 2020). "Collectively, this treatment strategy comprised of selective blockade of IL-6 signal with anti-IL-6R blocking antibody could be effective and ideal for treating PD-1 signal blockade-induced psoriasis-like dermatitis." (PMID 33060784, 2020).
psoriasis (continued). "Besides keratinocytes, fibroblasts and dermal mast cells are important sources, as shown for TNF-α in psoriasis and atopic dermatitis, and for IL-6 in psoriasis." (PMID 32927792, 2020). "Proinflammatory cytokines such as interleukin IL-1 and IL-6 were elevated in patients with psoriasis and depression, suggesting that inflammatory processes may be involved in the progression of both diseases." (PMID 32502022, 2020). "Furthermore, higher concentrations of TNFα and IL6 in the serum of obese patients with psoriasis are believed to be significant markers of psoriasis." (PMID 32443588, 2020). "Recent studies published by Wolk and Kiluk and colleagues point out that this type of tissue releases molecules directly associated with interplay between CMS and psoriasis: TNF-α (Tumor necrosis factor α), IL-6 (interleukin 6), leptin, resistin, vaspin, and omentin." (PMID 32456228, 2020). "Therefore, we employed blockade of IL-6 signaling using an anti-IL-6R blocking antibody (MR16-1) in order to assess the effects on IMQ-induced psoriasis-like dermatitis." (PMID 33060784, 2020). "However, daphnetin treatment attenuated IMQ-induced upregulation of those inflammatory cytokines in IMQ-induced psoriasis-like skin lesion at a certain extent, significantly reduced the expression of IL-6, IL-23A and IL-17A." (PMID 33081840, 2020). "Collectively, individuals with PD-1 signal blockade-induced psoriasis-like dermatitis can potentially benefit from IL-6-targeted therapeutic intervention, which is expected to inhibit both Th17 cell differentiation and cytotoxic CD8 T cell activation in the pathological mechanisms of irAE." (PMID 33060784, 2020). "In psoriasis, this impairment may be dependent on high IL-6 levels, as demonstrated by blocking IL-6 in co-cultures of Treg cells and effector T cells from psoriatic patients." (PMID 32161545, 2020). "Some studies have shown decreased levels of IL-17A, TNF-α, S100A15, S100A7, S100A9 and IL-6 gene expression in PBMCs after NB-UVB treatment in patients with psoriasis whereas other pro-inflammatory mediators such as sVCAM-1, sICAM-1, sE-selectin, MMP-9, and MPO showed no significant reduction." (PMID 30865695, 2019). "The induction fold of IL-6 following exposure to naringin or sericin alone was significantly lower than the untreated hPBMCs from psoriasis patients (9.6, 12.7 and 22.4 fold, respectively) and the effect was markedly seen with naringin/sericin combination (5.5 fold)." (PMID 31291937, 2019). "This study shows that the inflammatory response and immunostaining of IL-6, IL-17, and IL-23 are often similar in both GT and psoriasis, reinforcing the possibility that there is a type of GT that represents an oral manifestation of psoriasis." (PMID 31789253, 2019). "Previous studies have shown that psoriasis might also be mediated by IL–6, which provided a possible relationship between these two diseases." (PMID 31561576, 2019). "Results suggest that the anti-inflammatory activity observed following exposure of hPBMCs to naringin and sericin (24 h) could be via suppression of mRNA expression and production of TNF-α, IL-6, IL-12p40 and IL-23 cytokines in psoriasis patients." (PMID 31291937, 2019). "Genetic polymorphism of IL6 has been shown to be significantly associated with a form of psoriatic arthritis, and serum IL6 is considered as a biomarker for assessing disease activity in patients with psoriasis, as well as for predicting responsiveness of joint symptoms to biologic treatment." (PMID 30736745, 2019). "In addition, other pro‐inflammatory cytokines important in psoriasis, such as Il‐6, were only up‐regulated in non‐mutantTom cell populations (Fig EV4J), and we also observed that Il‐1β was significantly up‐regulated in non‐mutantTom b‐KCs (Fig EV4K)." (PMID 31556482, 2019).